EGFR (epidermal growth factor receptor)
Diseases named in the same sentence as EGFR in open-access papers (continued):
Sharing a sentence is not in itself a finding about the gene and the disease.
cancer (continued). "The authors conducted a meta-analysis of 13 studies containing 7328 cases and 8455 controls to estimate the association of R521K polymorphism in EGFR gene with risk of cancer." (PMID 25874199, 2015). "On the other hand, debate exists in regard to the selection or acquisition of this T790M mutation in EGFR gene in re-progressed cancer cells after treatment with EGFR-TKIs." (PMID 25714021, 2015). "About ten percent of NSCLC cancers harbor activating mutations in the Epidermal Growth Factor Receptor (EGFR) gene." (PMID 26022577, 2015). "These pathways, including the epidermal growth factor receptor (EGFR) pathway, are frequently hyperactivated in cancers through mutation or amplification and constitute so-called ‘oncogenic drivers’." (PMID 25852742, 2015). "Among different cancers, colorectal cancer patients receiving anti-EGFR MoAbs treatment showed the highest risk of electrolyte disorders compared with their controls." (PMID 25542231, 2015). "Several different somatic EGFR mutations have been shown to confer sensitivity to tyrosine kinase inhibition (TKI) in cancer models." (PMID 25969993, 2015). "EGFR signaling is commonly deregulated in cancer through different mechanisms, including genetic mutations of the receptor." (PMID 26308162, 2015). "Overexpression of EGFR by mutation, amplifications or misregulations is considered a key factor in the uncontrolled cell division of a number of cancer types." (PMID 26160836, 2015). "It was found that mutations leading to EGFR overexpression have been associated with many cancers, including lung cancer, anal cancers, and glioblastoma multiforme." (PMID 25961047, 2015). "MSI cases are generally characterized by accumulation of mutations in PIK3CA, ERBB3, ERBB2, and EGFR; along with mutations present in ‘hotspot’ sites that have been identified in other cancers." (PMID 26267324, 2015). "Future prospective clinical studies are warranted to confirm the prognostic importance of MLH1 V384D, as well as to define appropriate combinations of anti-cancer therapeutics in treating tumors with concomitant existence of EGFR L858R and MLH1 V384D alleles." (PMID 25823662, 2015). "The EGFR-mutated cancers were seen in 16 out of 24 tested female patients (67 %), all light or never smokers." (PMID 26582178, 2015). "An over-expression of EGFR has often been associated with a variety of human cancers that can provide the basic properties required for cancer growth, including cell proliferation, anti-apoptosis, metastasis and angiogenesis." (PMID 25885222, 2015). "Genomic alterations targeting the Epidermal Growth Factor Receptor (EGFR) gene have been strongly associated with cancer pathogenesis." (PMID 25826094, 2015). "To illustrate this analysis, we show the distribution of domain mutations in the EGF receptor, encoded by EGFR, across five cancers." (PMID 25794154, 2015). "EGFR expression has been linked to increased cell proliferation in several types of cancer and Ki67 is a marker that also indicates actively proliferating cells." (PMID 25714027, 2015). "Mutation of EGFR at Y1045 decreased WJ-induced growth inhibition as well as in vivo anti-cancer effect and EGFR degradation mediated by WJ." (PMID 25980579, 2015). "Altered EGFR signaling has been implicated in the emergence and progression of cancers by dysregulated and uncontrolled cell growth." (PMID 25885672, 2015). "We believe when internalized, cetuximab-IONPs accumulate and a pro-apoptotic signal is triggered, as the consequence of EGFR signaling dysregulation, through cleavage of caspase 9, followed by cleavage of caspase 3 that eventually causes cancer cell death." (PMID 25871395, 2015). "For example, EGFR and ErbB2 are mutated in many epithelial tumors and clinical studies suggest that they play an important role in cancer development and progression." (PMID 26635612, 2015).
cancer (continued). "EGFR is often found overexpressed or mutated in a wide variety of human cancers, and these events are closely linked to enhanced tumorigenicity." (PMID 25803810, 2015). "WJ inhibited-lung tumor growths in orthotopic and tail vein injected mouse models were abolished by Y1045 EGFR mutation, indicating the critical role of EGFR in the anti-cancer effect of HDAC inhibition." (PMID 25980579, 2015). "A retrospective review of EGFR mutation reflex testing experience for all ADC diagnosed at a tertiary Asian cancer centre from January 2009 to April 2013." (PMID 25955322, 2015). "This is consistent with our gene program analysis, where EGFR response was most strongly associated with poor survival in LUSC, and LUSC was consistently associated with GBM, which is a cancer known for EGFR dysreguation." (PMID 27047702, 2015). "Last but not least, as acquired resistance is a common problem of small molecule based anti-cancer therapy, we are dedicated to investigating solutions to prevent or overcome acquired resistance associated with EGFR and BRAFV600E targeted therapy." (PMID 26023796, 2015). "Amplification of the EGFR gene and mutations of the EGFR tyrosine kinase domain have been recently demonstrated to occur in carcinoma patients." (PMID 26648665, 2015). "Enhanced signalling via the epidermal growth factor receptor (EGFR) is a hallmark of multiple human carcinomas." (PMID 26526352, 2015). "We then apply the multiple classifier to identify and test the functional impact of rare cancer-associated mutations in EGFR." (PMID 24743239, 2014). "As in that case report, our patient exhibited sensitivity to erlotinib in brain metastases, even though the cancer cells in the pleural effusion had acquired a resistant mutation to EGFR-TKI, T790M." (PMID 24555578, 2014). "The same are also differentially linked to NM_201284 of EGFR in agreement with the earlier observation (NM_201283 and NM_201284 have edges only in cancer samples)." (PMID 25034693, 2014). "Recently, several studies have reported that this phenomenon is strongly associated with cancer cell stemness and resistance to drugs such as EGFR-TKIs." (PMID 25096400, 2014). "The epidermal growth factor receptor family, which consists of EGFR/Her1, Her2, Her3 and Her4, has been implicated in a variety of different cancer types." (PMID 25594026, 2014). "Increased EGFR signaling is linked to cancer and abnormal EGFR expression is found in approximately 80% of cases of NSCLC." (PMID 24456610, 2014). "In the current study, we reviewed all literatures regarding EGFR R521K polymorphism in cancer and conducted a meta-analysis to identify the association between the R521K polymorphism and the risk of cancer." (PMID 25401099, 2014). "This allowed us to explore new features beyond the original CRISPR/Cas9 knockout screen design, for example, to identify new drug response genes and potential combination therapies (for example, EGFR in BRAF mutated cancer cells)." (PMID 25476604, 2014). "Expression of NTS/NTSR1 on breast tumoral cells creates a cellular context associated with cancer aggressiveness by enhancing epidermal growth factor receptor activity." (PMID 25249538, 2014). "EGFR is overexpressed or constitutively activated in many types of human cancers, associated with a poor prognosis." (PMID 25000529, 2014). "EGFR dysregulation is associated with multiple cancer types including malignant transformations and metastasis." (PMID 24811863, 2014). "EGFR signaling has been implicated as a mechanism of resistance to several targeted cancer therapies, such as crizotinib, trastuzumab, and vemurafenib." (PMID 25053989, 2014). "Trafficking defects resulting in mislocalization and poor downregulation of the EGFR are associated with enhanced signaling, which can lead to the development of cancer." (PMID 24295852, 2014).
cancer (continued). "Mutations of EGFR have been identified in several types of cancer 67, 68, 69, and the EGFR is the target for an expanding class of anticancer therapies." (PMID 24295852, 2014). "Given the role of cetuximab in therapy of these cancers, initial efforts to identify activating EGFR mutations identified few such events, though potentially activating events such as G719S were seen." (PMID 24894453, 2014). "The epidermal growth factor receptor (EGFR) plays a key role in regulating cell proliferation, migration, and differentiation, and aberrant EGFR signaling is implicated in a variety of cancers." (PMID 25058506, 2014). "The aberrant expression of the HER family members and, in particular, EGFR has been reported in a wide range of human cancers and has been associated with metastasis and poor prognosis." (PMID 24609222, 2014). "Several well-known oncogenic pathways have been implicated in the pathogenesis of cancers, including the epidermal growth factor receptor (EGFR), hepatocyte growth factor receptor (HGF/c-Met), and vascular endothelial growth factor (VEGF) pathways." (PMID 25268742, 2014). "A likely explanation for these findings was that the resistance process was torpid during the enrichment of resistant cancer cells carrying de novo T790M mutation, which leaded to a long EGFR-TKI sensitive phase." (PMID 25405807, 2014). "AMSH (associated molecule with the SH3 domain of STAM) expression is elevated in many cancers and is capable of hydrolyzing K63-linked Ub chains from epidermal growth factor receptor (EGFR) recycling it to the plasma membrane." (PMID 25121098, 2014). "The EGFR has been strongly implicated in the biology of human epithelial malignancies, with therapeutic applications in cancers of the colon, head and neck, lung, and pancreas." (PMID 24454732, 2014). "In particular, our studies suggest T725M as a likely cancer-associated mutation because it increases EGFR auto-phosphorylation activity in comparison to wild-type and other activating mutations such as L858R." (PMID 24743239, 2014). "Mutations in the extracellular domain of EGFR is often associated with the amplification of genes in other cancers." (PMID 24760004, 2014). "Previous studies have shown that hypoxia mediates the resistance to EGFR-TKIs in EGFR-mutated NSCLC via an EGFR signal or cancer cell stemness." (PMID 25096400, 2014). "Incubation with the phosphatidylcholine nanoparticles prepared in neutral buffer was associated with increased EGFR content in the cancer cells and with its altered cellular localization." (PMID 24772432, 2014). "For example, nuclear EGFR has been detected in a number of human cancers including breast, oropharyngeal, bladder, pancreatic, ovarian, lung and colorectal, and nuclear EGFR has been associated with acquired resistance to chemotherapy and poor prognosis." (PMID 25416285, 2014). "Mutations that lead to EGFR overexpression or overactivity have been associated with a number of cancers, including lung cancer, anal cancers and the glioblastoma multiforme." (PMID 24658383, 2014). "Genetic variants of EGFR have also been shown to influence clinical outcome of many different types of cancer including non-small-cell lung cancer (NSCLC), prostate cancer, metastatic colorectal cancer (mCRC), and pancreatic cancer." (PMID 24945674, 2014). "EGFR dysfunction has been implicated in a variety of cancers, and EGFR-targeting drugs are commonly used in cancer treatments." (PMID 25058506, 2014). "Here we combine computational and experimental approaches to identify rare cancer-associated mutations in Epidermal Growth Factor receptor kinase (EGFR), a signaling protein frequently mutated in cancers." (PMID 24743239, 2014). "Outside of the identification of rarely occurring epidermal growth factor receptor and v-kit Hardy-Zuckerman 4 feline sarcoma viral oncogene homolog mutations via candidate gene sequencing, mutations in common cancer genes have yet to be observed." (PMID 25000259, 2014).
cancer (continued). "Of particular interest to our research is the epidermal growth factor receptor (EGFR), the activation and overexpression of which has been linked to malignant transformation and progression of a broad variety of cancers." (PMID 25471819, 2014). "Given the criticality of EGFR mutation testing in selecting specific therapies for life-threatening cancers such as advanced NSCLC, robust and accurate assays with rapid turnaround time are preferred." (PMID 24586842, 2014). "Here we report the results of structural modeling and dynamics analysis of the activating cancer mutations in EGFR L858R and L861Q." (PMID 24817905, 2014). "It is well known that cancer driver genes, such as EGFR, are over-expressed or activated by mutations in tumors, further activating downstream pathways associated with cell growth and survival." (PMID 24646369, 2014). "SOX2 is intricately involved in many cancer-associated processes such as cell proliferation, evading cellular apoptosis and metastasis via interactions with EGFR signaling and several other oncogenic pathways and processes." (PMID 25114775, 2014). "Other studies involving different types of cancer also point to an interaction between the two EGFR polymorphisms, with a combined protective effect in relation to disease progression." (PMID 24629097, 2014). "In many cancer cells, over-expression or over-activation of growth factor receptors (i.e. EGFR, PDGFR) causes Akt hyper-activation." (PMID 24886166, 2014). "For example, recent studies showed that cancer mutations alter the temporal regulation and phosphorylation rates of the C-terminal tail tyrosines in EGFR." (PMID 24743239, 2014). "The role of EGFR overexpression/mutation and new modulators of EGFR traffic in cancer and the response to cancer therapeutics are also discussed." (PMID 24295852, 2014). "This mutation in the EGFR activates the kinase by disrupting auto-inhibitory interactions leading to a ligand-independent activation of TK activity and thus causes cancer." (PMID 24992720, 2014). "GM3, a sialic acid-containing GSL whose expression is reduced in transformed cells, inhibits EGFR activation, a process associated with cancer cell growth and motility." (PMID 24944646, 2014). "EGFR signaling has been linked to survivin in many cancer studies, and it has been shown that EGFR activates the PI3K/Akt pathway leading to upregulation of HIF-1alpha which subsequently activates survivin gene expression by binding to its promoter region." (PMID 24695557, 2014). "EGFR (epidermal growth factor receptor) is activated through changes in expression or mutations in a number of tumors and is a driving force in cancer progression." (PMID 25594057, 2014). "Activated SRC phosphorylates a diverse spectrum of substrates that results in up-regulation of several cancer-associated pathways including EGFR signaling." (PMID 25301722, 2014). "Constitutive activation of EGFR- and NF-κB-dependent pathways is a hallmark of cancer, yet signalling proteins that connect both oncogenic cascades are poorly characterized." (PMID 25366117, 2014). "Real-time PCR-based methods have been shown to efficiently detect EGFR mutations in samples containing 1% mutated cancer cells." (PMID 24236184, 2013). "Dysregulation of EGFR signaling as a consequence of overexpression, amplification and mutation of the EGFR gene occurs frequently in several types of cancers and many become dependent on EGFR signaling to maintain their malignant phenotypes." (PMID 24349829, 2013). "This study aims to explore current testing practices, logistics of testing, types of EGFR mutation, and prevalence of EGFR mutations in patients with advanced NSCLC in a large comprehensive cancer center in Korea." (PMID 23468851, 2013). "In accordance with the increase in the frequency of testing over time, the turn-around time from cancer diagnosis to EGFR mutation report progressively decreased, facilitating the clinical use of test results." (PMID 23468851, 2013).
cancer (continued). "A series of novel 6-salicyl-4-anilinoquinazoline derivatives 9–27 were prepared and evaluated for their EGFR/HER2 tyrosine kinase inhibitory activity as well as their antiproliferative properties on three variant cancer cell lines (A431, MCF-7, and A549)." (PMID 23936329, 2013). "Cancers with PTEN deletion or mutation are frequently resistant to targeted anticancer agents that function upstream of PTEN such as those against epidermal growth factor receptor." (PMID 24312263, 2013). "This signature set was also found to associate with the efficacy of the anti-cancer drug ZD-6474 targeting EGFR." (PMID 24369726, 2013). "We have previously shown that distinct oncogenic mutations in EGFR deploy differential pathway utilization in cancer cells, which has therapeutic implications in the clinic." (PMID 23822953, 2013). "The variant III mutant of EGFR (EGFRvIII) is the most common deletion mutant of EGFR in human cancer and its levels are highly correlated with poor prognosis in GBM." (PMID 23408876, 2013). "Mutations that lead to epidermal growth factor receptor over-expression (known as upregulation) or over-activity have been associated with a number of cancers." (PMID 23825632, 2013). "Our study is limited by the lack of information regarding the EGFR mutation status in our patients; however, most cancer-associated EGFR mutations occur in adenocarcinomas of the lungs." (PMID 23647947, 2013). "EGFR overexpression has even been associated with embryonal rhabdomyosarcomas, a type of cancer in which malignant cells arise from muscle precursor cells, and proposed as a biomarker for their diagnosis." (PMID 23967242, 2013). "Epidermal growth factor receptor (EGFR) is involved in diverse cellular processes, including proliferation and motility; however, it is also implicated in the development of various human cancers." (PMID 23924390, 2013). "In a similar fashion, aberrant activation of EGFR signaling has been implicated in the development and progression of many human cancers." (PMID 23688423, 2013). "In some human cancers receptor tyrosine kinases such as EGFR are in a constitutively active form due to mutations that abrogate the quiescent, non-aggregated state of the receptor." (PMID 23894364, 2013). "Despite the fact that Mig6/EGFR was highly associated with EGFR activity in cancer cell lines of multiple tissue types, depleting Mig6 per se in these cells failed to alter basal EGFR activity and the response to erlotinib in an unstimulated environment." (PMID 23935914, 2013). "EGFR-TKI has been clinically used in cancer patients although it is occasionally associated with severe side effects, including acute interstitial pneumonia." (PMID 23592411, 2013). "There does not appear to be any difference between HPV-associated and HPV-negative cancers with regard to EGFR expression." (PMID 24364026, 2013). "The EGFR pathway induces pro-proliferative and anti-apoptotic signals, and constitutes a convenient target for somatic mutation in cancer." (PMID 24152305, 2013). "Higher levels of IL-6 and EGFR in HNSCC cancer patients’ serum are found to be associated with a higher second primary cancer (SPC) specific mortality and hence established as serum biomarkers for HNSCC." (PMID 23414419, 2013). "MUC1 associates with β-catenin, NF-κB and EGFR and translocates to the nucleus thereby regulating transcription of several genes responsible for progression and invasiveness of cancer." (PMID 24072600, 2013). "In particular, the interaction of Src and EGFR has raised much interest because both are ubiquitously expressed and their co-overexpression and/or mutations have often been found in cancer cells of humans and model animals." (PMID 23702846, 2013).